INS (insulin)
Diseases named in the same sentence as INS in open-access papers (continued):
Sharing a sentence is not in itself a finding about the gene and the disease.
Insulin resistance (continued). "Impaired insulin signaling is the central feature of the metabolic syndrome (MS); insulin resistance is often associated with hypertension, especially salt-sensitive hypertension; this association may promote cardiovascular (CV) diseases and microvascular complication in type II diabetes mellitus." (PMID 32851077, 2020). "Furthermore, it may explain how insulin resistance can affect the integrity of the glomerular filtration barrier in kidney disease associated with and insulin resistant states, such as DKD." (PMID 33458251, 2020). "This higher susceptibility to develop insulin resistance under conditions of energy oversupply were manifested by a set of alterations found in male mice: reduced glucose disposal rate following glucose load, lower response to insulin, hyperinsulinemia and islet hypertrophy." (PMID 32183232, 2020). "Causes for brain insulin resistance development in DS could be various, considering that DS phenotype shows both peripheral and brain alterations that would trigger the impairment of the brain insulin signaling pathway." (PMID 32733190, 2020). "Moreover, it was stated that the intensity of hyperinsulinemia and insulin resistance (which has a great effect on the phenotype of PCOS) is further influenced by both genetic factors (such as polymorphism in the insulin gene regulatory region) and environmental factors, especially obesity." (PMID 32429890, 2020). "Hence, if ADA activity is inhibited, insulin sensitivity may be improved, and processes associated with the pathophysiology of insulin resistance such as cellular proliferation, inflammation, and T-cell activity can also be affected." (PMID 33053898, 2020). "Increasing evidence suggests that vitamin D may play an important role in modifying the risk of diabetes, as vitamin D acts directly on the pancreatic beta cell by increasing insulin secretion, and indirectly by attenuating systemic inflammation that is associated with insulin resistance." (PMID 33036170, 2020). "Similarly, 40 h-continuous infusion of insulin resulted in reduced glucose utilization in humans, and more recently hyperinsulinemia has been demonstrated to be the predominant causative factor leading to insulin resistance in type 1 diabetic subjects." (PMID 32718202, 2020). "mTOR may also cause neuronal insulin resistance, glucose deficiency (because insulin and amino acids directly affecting mTOR are the main regulators of ATG), and consequently reduced glucose metabolism, abnormal ATP production, as well as dysfunction and/or death of the cells." (PMID 32121669, 2020). "The elevation in insulin sensitivity may be attributed to the anti-inflammatory action of αT in visceral adipose tissue, by reducing the level of p38 phosphorylation, which is associated with many inflammatory responses and insulin resistance." (PMID 32903449, 2020). "Whole-body insulin action and muscle insulin sensitivity were investigated to determine whether inducible deletion of muscle AMPKα in adult mice was associated with the development of insulin resistance." (PMID 32504885, 2020). "Indeed, prior research has shown that increases in circulating branched chain amino acids are associated with insulin resistance in obese patients, which is relevant for this dataset investigating the effect of Glut4 on insulin sensitivity in white adipose tissue." (PMID 32093613, 2020). "If this mechanism extends to humans, the insulin resistance that underlies metabolic syndrome and associated female infertility (reviewed) may be connected to the inability of insulin to affect the ability of ovarian hormones (E2 and P4) to properly change carbohydrate use in uterine tissues." (PMID 32239183, 2020). "In addition to impaired insulin responsiveness of adipocytes, being overweight may also cause lipodystrophy and insulin resistance by reducing the expression of lipid droplet proteins in adipocytes." (PMID 33014044, 2020).
Insulin resistance (continued). "Our data suggest that a bout of exercise may curb the compensatory hyperinsulinemia which is associated with progression of insulin resistance by reducing demand for insulin secretion, and this effect is enhanced with the addition of intermittent breaks in sitting." (PMID 33308235, 2020). "Altogether, we could conclude that SGLT2 inhibitors plus insulin therapy is an efficient treatment option for patients with T2D, especially those requiring high daily insulin doses and those with insulin resistance, obesity, and a high risk of cardiovascular events." (PMID 32351447, 2020). "To date, scientists have revealed that one of the central pathogenic mechanisms of insulin resistance is the modulation of inflammation-related factors, which affects the gene expression regulation and metabolism of some lipid-related factors involved in the insulin signalling pathway." (PMID 33292292, 2020). "During the progression of insulin resistance, decreased glucose-intake in adipose tissues and muscles, compounded by enhanced gluconeogenesis and glycogenolysis in the liver, may cause chronic high blood glucose levels leading to increased insulin demand." (PMID 32375753, 2020). "Therefore, in GDM, associated with insulin resistance, hyperinsulinemia and hyperleptinemia, flavonoids might downregulate the synergistic interaction between insulin and leptin signaling in the inflammatory processes." (PMID 32630697, 2020). "Finally, if an association between insulin resistance and COVID-19 severity was established, the next step would be to determine whether strategies to enhance insulin sensitivity acutely (such as carbohydrate restriction) could improve prognosis." (PMID 32574288, 2020). "This in vitro result also mirrors insulin resistance as it occurs in vivo as insulin resistance in humans is also associated with higher circulating free fatty acids that can promote ectopic fat accumulation hence further worsening insulin sensitivity at the whole-body level." (PMID 32718202, 2020). "Taken together, these data suggest a possible relationship between inflammatory processes, apoptotic pathways, and insulin signalling impairment, which characterize obese subjects and may explain the increased susceptibility of these individuals to developing insulin resistance." (PMID 33260451, 2020). "Also, insulin resistance contributes to the CVDs promoting atherogenesis and plaque progression via multiple mechanisms, including changes in classic risk factors of CVDs and downregulation of insulin signaling pathways." (PMID 33182462, 2020). "T2D is characterized by obesity-induced insulin resistance, and proinflammatory response in insulin-sensitive peripheral tissues, including liver, adipose tissue, and muscle, plays an essential role in the pathogenesis of T2D such as obesity-induced insulin resistance and associated complications." (PMID 33003609, 2020). "Moreover, cohort and cross-sectional studies demonstrated that BMI and WHR were associated with glycemic traits, including fasting insulin, Hemoglobin A1c (HbA1c), and insulin resistance [measured by Homeostatic model assessment of insulin resistance (HOMA-IR)]." (PMID 32714368, 2020). "This large difference in the number of genes between HOMA-β and HOMA-IR strengthens the hypothesis that defects in insulin secretion are caused by a large number of genes and may have a large genetic component, while insulin resistance may largely be induced by environmental factors." (PMID 32294959, 2020). "In addition, inflammation may cause insulin resistance through the direct action of TNFα on muscle insulin signaling." (PMID 33841133, 2020). "Furthermore, a majority of them did not clearly converge on the functional categories consistent with known aspects of T2D pathophysiology, i.e., impaired insulin secretion and insulin resistance in peripheral tissues—the two hallmark glycemic intermediate traits of T2D." (PMID 32294959, 2020).
Insulin resistance (continued). "In this respect, amelioration in insulin resistance and glucose metabolism occurred soon after the procedure, when significant weight loss had not yet been achieved, suggesting the involvement of gut hormonal mechanisms such as increased secretion of incretins that enhance insulin sensitivity." (PMID 33019725, 2020). "Similarly, in a study including 299 pregnant women (participants of the NHANES 2001–2010 study), urinary concentrations of total isoflavone metabolites were inversely associated with fasting plasma glucose (FPG), insulin, and homeostatic model assessment of insulin resistance (HOMA-IR)." (PMID 33379327, 2020). "In addition, the methylation site was previously found to act as an integral part of insulin and glucose metabolism, as well as associating with homeostatic model assessment for insulin resistance (HOMA-IR), a commonly used surrogate to define the state of insulin resistance." (PMID 33239708, 2020). "We hypothesised that RYGB-D FMT leads to increased insulin sensitivity, in conjunction with faster intestinal transit time, as this would provide less opportunity for the bacterial translocation associated with inflammation and insulin resistance." (PMID 31147381, 2020). "Thus, elucidating the mechanistic processes underlying insulin signaling may improve our understanding of the development of alcohol-induced insulin resistance." (PMID 32508647, 2020). "Thus, emerging questions are as follows: in which way is the higher Tmax of diabetic patients related to insulin resistance, hyperinsulinaemia, or insulin deficiency; and which are the relationships between the insulin signalling and PTs glucose transport proteins activity." (PMID 32377524, 2020). "Increased TSH levels may cause altered adipocyte physiology which causes the decreased release of insulin-sensitizing adipokines, such as adiponectin, that may lead to insulin resistance and associated comorbidities, such as the future development of type II diabetes mellitus (DM)." (PMID 32550062, 2020). "Although insulin itself exhibits sympatho-excitatory effects, renal denervation allows examination of the direct role of the sympathetic nervous system, without causing further systemic pharmacological interactions, in mediating insulin resistance and its consequences." (PMID 31963760, 2020). "Moreover, they do not assess whether seasonal changes might affect individuals with different disease conditions, for example, insulin sensitive (IR) versus insulin resistant (IR) individuals (insulin resistance is often associated with Type 2 diabetes)." (PMID 33004787, 2020). "As mitochondrial dynamics and biogenesis are impaired in these cells in the face of insulin resistance and in type 2 diabetes, it is conceivable that preserving the normal function of mitochondria may slow the loss of normal insulin secretion and disease progression." (PMID 32350566, 2020). "Moreover, hs-CRP has been reported to be associated with insulin resistance, insulin index and GDM." (PMID 31419950, 2019). "Conventional wisdom suggests that obesity and the development of type 2 diabetes are associated with insulin-resistance and a compensatory increase in insulin levels could then stimulate the growth and metabolism of neoplastic cells via insulin receptors, IR-A or hybrid IGF-I/IR receptors." (PMID 30809194, 2019). "Individuals with impaired insulin secretion and moderate insulin resistance are labelled under group 2 (the severe insulin-deficient diabetes group) while in group 3, the severe insulin-resistant diabetes patients with obesity and severe insulin resistance are included." (PMID 31827713, 2019). "The real possibility exists that hyperinsulinism (either due to insulin resistance or, in this case, having an iatrogenic component) may be associated with an increased anti-fibrinolytic status, as insulin stimulates the Plasminogen Activator Inhibitor-1 (PAI-1) production in adipocytes." (PMID 31540142, 2019).
Insulin resistance (continued). "Therefore, the hyperinsulinemia of these mice may be attributed at least in part to SIRT3 deficiency caused insulin hypersecretion from β-cells, which accelerates the development of insulin resistance and metabolic syndrome." (PMID 30683850, 2019). "A cell-based study suggested that soy protein and isoflavones are beneficial for reducing the risk of onset and development of insulin resistance and T2D and a review also showed that fermented soy products may attenuate the progression of T2D by improving insulin resistance and insulin secretion." (PMID 31731672, 2019). "Some preclinical studies have suggested that uric acid might directly influence fat accumulation and hepatic steatosis by inhibiting insulin signaling to cause insulin resistance, inducing mitochondrial oxidative stress or generating endoplasmic reticulum stress." (PMID 31523513, 2019). "Another mechanism that could explain the elevated risk of GDM is that whole grains and seafood might contain more arsenic and other environmental contaminants, which have been shown to be associated with increasing insulin resistance and impairing insulin production." (PMID 30769927, 2019). "To study the compensatory mechanisms associated with insulin resistance and the impact of the hepatic expression of IR isoforms on this response, we performed immunohistochemical analysis of pancreatic sections from all the groups studied by staining with anti-insulin antibodies." (PMID 30642871, 2019). "Moreover, serum irisin level was negatively associated to HOMA-IR and fasting insulin, suggesting that irisin may play a role in obesity related insulin resistance." (PMID 31881940, 2019). "Moreover, impaired glucose metabolism may influence brain structure and function as peripheral insulin resistance is associated with reduced global and regional brain glucose metabolism and with the restrain of insulin transport into the brain." (PMID 30934836, 2019). "Thus, there must be a tight cross-regulation C/EBP-α, FOXO1 and PPAR-γ2 that modulates adipogenesis linked to insulin resistance in an alternative insulin pathway and common alternative pathway, since it has been reported that they physically interact, cooperate and activate each other." (PMID 31547433, 2019). "Similarly, other factors that reduce insulin sensitivity such as exposure to corticosteroids or acute stress may unmask underlying insulin resistance that was previously well-compensated." (PMID 31474943, 2019). "Therefore, ARL15 may either play a causative role in insulin resistance or an adaptive response to enhance insulin action." (PMID 31623319, 2019). "Acromegaly is also associated with decreased expression of the insulin-sensitizing adipokine adiponectin, but also with increased circulating concentrations of the proinflammatory adipokine visfatin, which is linked to enhanced inflammation and insulin resistance in many tissues." (PMID 31417493, 2019). "Finally, insulin resistance may also be directly involved in increases fibrosis, and variants in insulin signaling pathway genes may alter the risk of develop fibrosis." (PMID 31375010, 2019). "The potential association between decreased insulin resistance and reduced postprandial lipid dysmetabolism suggests that ezetimibe is the possible drug with regard to the vascular protective effects in such patients due to reduction in both insulin level and postprandial hyperlipidemia." (PMID 30519809, 2019). "The increase in free-fatty acids flux is implicated in the development of insulin resistance via the Randle cycle in the liver and muscles and through direct or indirect (derived from triglyceride deposits) generation of metabolites, which alter the insulin signaling pathway." (PMID 31640224, 2019).
Insulin resistance (continued). "Metabolic dysfunction, especially insulin resistance, is a key risk factor in the early development of AD and several attempts have been made to develop pharmaceutical treatments for AD by managing insulin signaling such as an intranasal insulin spray and GLP-1 agonists." (PMID 31009489, 2019). "The “paradoxical” cognitive improvement and protection against hypothalamic inflammation in aged GHR-knockout mice may be related to the higher insulin sensitivity observed in these animals as insulin resistance has been linked with impaired cognition and is a risk factor for Alzheimer’s disease." (PMID 31939479, 2019). "Particularly, AKT/protein kinase β appears to be a critical node in mediating the physiological effect of insulin, and impaired AKT signaling, as described in insulin-resistant individuals, may be involved in the pathogenesis of PD, further supporting its association with insulin resistance." (PMID 31787891, 2019). "Thus, independently of whether mitochondrial dysfunction is a cause or a consequence of insulin resistance, boosting mitochondrial function remains a promising strategy to improve insulin sensitivity." (PMID 31130874, 2019). "This increase could be due to an increase in adiposity as of this age (and fat inhibiting the effect of insulin), or a progressive increase in insulin-like growth factor-1 that takes place as puberty approaches and has effects associated with insulin resistance." (PMID 29402762, 2018). "It is possible that insulin resistance may cause changes in proliferative pathways activated directly by insulin or insulin-like growth factor-1 (IGF-1), which helps regulate thyroid gene expression and may be important in thyrocyte proliferation and differentiation." (PMID 29374470, 2018). "In addition to insulin resistance, the K121Q polymorphism was also proven to be associated with different obesity-related phenotypes such as percentage of body fat, fat mass, and plasma insulin levels." (PMID 30338250, 2018). "While long-term exposure to obesogenic stimuli and the low level of inflammation can cause insulin resistance in all insulin responsive tissues, the question whether endothelial insulin resistance might occur independently or indeed be a driver for systemic insulin resistance remains unanswered." (PMID 29209827, 2018). "Hence, if brain insulin resistance is a cause of AD, then detailed studies of brain insulin signaling might yield information regarding the alleviation of brain insulin resistance, which could lead to improvements in the prevention and treatment of AD." (PMID 29673239, 2018). "We hypothesized that higher levels of early childhood abuse would be associated with higher levels of insulin resistance, as demonstrated by higher fasting insulin levels, higher fasting glucose levels, and a persistently elevated glucose curve after an oral glucose tolerance test (OGTT)." (PMID 30622489, 2018). "Furthermore, lipidomic associations with AAP treatment and insulin sensitivity may suggest that underlying changes in skeletal muscle lipid composition may play a role in AAP-associated insulin resistance." (PMID 30322152, 2018). "Insulin positively regulates synthesis of intestinal apo A-IV as well as secretion, which may cause an increase of this protein at the high insulin levels in the presence of insulin resistance." (PMID 29960584, 2018). "This may be caused by improved beta cell function with stimulation of insulin secretion and an increase in glucagon-like peptide-1 secretion, which participates in glucose homeostasis by lowering plasma glucose concentration and improving insulin resistance." (PMID 30274359, 2018). "Therefore, in this study, we investigated whether insulin-deficient diabetes may inhibit the wound healing process related to the hyperglycemia-induced insulin resistance." (PMID 30439990, 2018).